NSUN2 (NOP2/Sun RNA methyltransferase 2)
Diseases named in the same sentence as NSUN2 in open-access papers (continued):
Sharing a sentence is not in itself a finding about the gene and the disease.
breast cancer (continued). "Upregulation of NSUN2 promotes proliferation, migration, and invasion of breast cancer cells, whereas NSUN2-KO inhibits these processes." (PMID 35562754, 2022). "In breast cancer cells and tissues, NSUN2 DNA hypomethylation leads to overexpression of NSUN2 mRNA and protein." (PMID 35562754, 2022). "The immunohistochemical image showed moderate NSUN2 expression in normal breast glands and high expression in breast cancer tissues." (PMID 33928086, 2021). "In breast cancer, NSUN2 is a MYC target gene, which is closely related to cell growth and proliferation." (PMID 33928086, 2021). "Analysis of the association between clinical pathology and NSUN2 expression in breast cancer samples in the UALCAN database showed that NSUN2 was highly expressed in breast cancer." (PMID 33928086, 2021). "The results showed higher NSUN2 expression in breast cancer tissues than in normal tissues (p = 6.38e–09)." (PMID 33928086, 2021). "This shows that NSUN2 is a powerful and clinically significant biomarker in breast cancer and can be used as a potential therapeutic target for breast cancer." (PMID 34195072, 2021). "We performed GSEA to identify the abnormally activated signaling pathways of NSUN2 and NSUN6 that cause their differential expression in breast cancer." (PMID 33928086, 2021). "In one early study, elevated protein expression of NSUN2 was confirmed in various cancers including esophageal, stomach, liver, pancreas, uterine cervix, prostate, kidney, bladder, thyroid, and breast cancer." (PMID 32708015, 2020). "The upregulation of NSUN2 at the protein level in breast cancer was subsequently confirmed by Tatsuka and colleagues." (PMID 32708015, 2020). "Given that alterations involving increased expression of NSUN2 are common in breast cancer, colon cancer, and lung cancer as suggested in the suggestions above, molecularly targeting this RNMT would appear to an attractive approach moving forward." (PMID 32708015, 2020). "Similar to our result, NSUN2 has been found to be significantly correlated with clinical stage and pathological differentiation in breast cancer." (PMID 33365328, 2020). "In their original report on NSUN2, Frye and Watt observed that NSUN2 was overexpressed in 7/7 human breast carcinomas." (PMID 32708015, 2020). "Frequent hypomethylation of the NSUN2 promoter region in breast cancer tissues, even in the low-grade tumors, is comparable to the hypomethylation frequencies of known oncogenes in breast and other types of tumors." (PMID 27447970, 2017). "The overexpression of NSUN2 in breast cancer cells has been reported in several studies, but the underlying mechanism has remained unidentified." (PMID 27447970, 2017). "The mRNA levels of NSUN2 in six breast cancer cell lines were also higher than that in MCF-10A (P<0.05)." (PMID 27447970, 2017). "In this study, we showed that the elevated expression of NSUN2 is correlated with the poor prognosis in breast cancer patients." (PMID 27447970, 2017). "Real-time PCR analysis, using 10 pairs of matched breast cancer and normal tissues, showed that NSUN2 was overexpressed (P<0.05) in 100% (10/10) of breast cancer patients, which is consistent with the data obtained from Oncomine database." (PMID 27447970, 2017). "In this study, we firstly report NSUN2 expression levels in breast cancers of different clinicopathological grades, and show that NSUN2 expression correlates with the clinical staging, tumor classification, and pathological differentiation." (PMID 27447970, 2017). "A systematic analysis of NSUN2 promoter methylation levels in human breast cancer cell lines showed that these levels are lower than that in the normal breast epithelial cells." (PMID 27447970, 2017). "We performed in silico analysis using data from UCSC gene browser and TCGA, found a 156 bp long CpG island in NSUN2 promoter region, and showed that this promoter is hypomethylated in breast cancer tissues." (PMID 27447970, 2017).
breast cancer (continued). "In summary, we showed that NSUN2 is a strong and clinically meaningful biomarker in breast cancer, whose expression correlates with the cancer clinical stage, ER and PR status, and Ki67 expression." (PMID 27447970, 2017). "The overexpression of NSUN2 was shown to significantly increase cell proliferation, migration, and invasion of breast cancer cells." (PMID 27447970, 2017). "To investigate if NSUN2 promotes metastasis and invasion of breast cancer, we performed migration assays and invasion assays in breast cancer cells." (PMID 27447970, 2017). "IHC analyses showed that 54 of 60 (90.0%) ER-negative paraffin-embedded breast cancer tissue samples displayed moderate or strong NSUN2 nuclear staining, whereas 56 of 131 (42.7%) ER-positive tumor demonstrated a decreased rate of NSUN2 staining (P<0.001)." (PMID 27447970, 2017). "Results from TCGA data analysis showed that there was significantly low methylation of NSUN2 in breast cancer tissues, and that there was the low methylation of whole NSUN2 DNA and high NSUN2 mRNA expression in tissues in breast cancer." (PMID 27447970, 2017). "To validate the expression of NSUN2 in breast cancer cells and tissues, we examined the protein levels of NSUN2 using Western blot." (PMID 27447970, 2017). "Overall, these results suggested that NSUN2 was epigenetically overexpressed due to DNA hypomethylation in breast cancer cells." (PMID 27447970, 2017). "NSUN2 expression was shown to be significantly higher in breast cancer cells and tissues than in normal breast epithelial cells and tissues, at both mRNA and protein levels." (PMID 27447970, 2017). "Furthermore, the upregulation of NSUN2 and NOP2 mRNA was significantly associated with shorter disease-free survival in breast cancer patients." (PMID 35562754, 2022). "Furthermore, the overexpression of NSUN2 induced by DNA hypomethylation promoted the proliferation, invasiveness and migration of breast cancer cells." (PMID 35721510, 2022). "In addition, several studies have reported high expression of NSUN2 in certain types of neoplasms including breast cancer, colorectal cancer, and lung cancer." (PMID 35280737, 2022). "Moreover, elevated protein expression of NSUN2 was found in various types cancers, including the esophageal, stomach, liver, pancreas, uterine cervix, prostate, kidney, bladder, thyroid, and breast cancers by immunohistochemistry (IHC) analysis." (PMID 32332707, 2020). "NSUN2 as a tRNA methyltransferase, is significantly related to cancer progression in several tumors, such as esophageal squamous cell carcinoma, breast cancer, and ovarian cancer." (PMID 32071816, 2020). "Similarly, NSUN2 was overexpressed in breast cancer and in head and neck squamous cell carcinoma, and its expression levels were correlated with cancer development and progression." (PMID 32393790, 2020). "Several studies have now shown that NSUN2 is overexpressed in breast cancer." (PMID 32708015, 2020). "Therefore, the results in vivo were consistent with our results in vitro, which further confirmed that NSUN2 played an important role in enhancing the tumorigenicity of breast cancer cells." (PMID 27447970, 2017). "Taken together, these results indicated that there was overexpression of NSUN2 in breast cancer." (PMID 27447970, 2017). "Therefore, to explore mechanism of NSUN2 overexpression in breast cancer, we assessed methylation level of NSUN2 gene promoter in six breast cancerous and one non-cancerous cell lines." (PMID 27447970, 2017). "Our findings additionally indicate that NSUN2 is involved in breast cancer progression and that it may be used as a potential therapeutic target in breast cancer." (PMID 27447970, 2017). "To determine whether NSUN2 expression promotes tumorigenicity in breast cancer cells in vivo, we established a xenograft model by inoculating nude mice (n=5/group) with MDA-MB-231/shNSUN2 or empty vector." (PMID 27447970, 2017).
breast cancer (continued). "Therefore, in vivo results were consistent with our results obtained in vitro, further confirming that NSUN2 plays an important role in the tumorigenicity of breast cancer cells." (PMID 27447970, 2017). "Together, all these results suggested that NSUN2 was related to progression of breast cancer." (PMID 27447970, 2017). "Our findings provide a unique insight into the roles and effects of NSUN2 overexpression in breast cancer cells, and highlight the necessity of the investigation of novel therapeutic targets, such as NSUN2, for the improvement of breast cancer treatments." (PMID 27447970, 2017). "All in all, these results confirmed that NSUN2 promoted proliferation of breast cancer cells." (PMID 27447970, 2017). "Taken together, the results presented here strongly suggest that NSUN2 plays an important role in development and progression of breast cancer, and that NSUN2 may be a novel therapeutic target." (PMID 27447970, 2017). "Our findings unveiled the oncogenic role of NSUN2 in the development and progression of breast cancer, and suggest that NSUN2 might be a novel prognostic marker and therapeutic target." (PMID 27447970, 2017). "Similarly, in breast cancer and melanoma, NSUN2 overexpression correlates with advanced stage and metastasis; NSUN2 can methylate mRNAs or even tRNA-derived fragments that regulate cell motility and cytoskeletal dynamics, thereby facilitating metastatic spread." (PMID 41301491, 2025). "As an m5C methyltransferase with unique mRNA catalytic activity, NSUN2 was found to be highly expressed in multiple cancers including gastric, bladder, gallbladder, and breast cancers, suggesting that NSUN2 might exert oncogenic properties through affecting m5C levels in cancer cells." (PMID 35280737, 2022). "However, the functional role of NSUN2 in breast cancer tumorigenesis and clinical staging remains unknown." (PMID 27447970, 2017). "NSUN2 and NSUN6 influence tumorigenesis and the tumor immune microenvironment (TIM) in breast cancer." (PMID 40370440, 2025). "Expression of NSUN1, NSUN2, NSUN5, DNMT1, DNMT3A, DNMT3B, and ALYREF was significantly increased, but DNMT2 and TET2 expression was markedly decreased in breast cancer tissues when compared with normal breast tissues." (PMID 35812757, 2022). "The result demonstrated that most of these m5C regulators, except NSUN2, NSUN7, and DNMT2, were overexpressed in breast cancer." (PMID 35812757, 2022). "This further confirms that NSUN2 and NSUN6 are related to the tumorigenesis of breast cancer, consistent with the findings of previous studies." (PMID 33928086, 2021). "The expression levels of NSUN2 and NSUN3 are downregulated by knocking out proto-oncogenic isozymes (sphingosine kinases 1 and 2, SK1 and SK2) in metastatic prostate cancer and breast cancer." (PMID 34512153, 2021). "The analysis of the cBioPortal database in this study showed that NSUN2 and NSUN6 have a high frequency of gene alterations in breast cancer patients." (PMID 33928086, 2021). "Five genes (DPH2 G3BP1, G3BP2, NSUN2, and TTC17) were similarly regulated by SK1 KD in prostate and breast cancer cells." (PMID 30971929, 2019). "NSUN2/YBX1 synergistically upregulate HGH1 mRNA stability and promote breast cancer progression." (PMID 40370440, 2025). "NSUN2 and NSUN6 affect tumorigenicity and the tumor immune microenvironment (TIM) of breast cancer." (PMID 35562754, 2022). "Interestingly, in the analysis by molecular subtype, NSUN2 expression was significantly higher in TNBC samples than in both normal samples and luminal breast cancer samples (p = 4.12e-10, 1.11e-6, respectively)." (PMID 33928086, 2021). "To determine the mechanism by which NSUN2 and NSUN6 affected the prognosis of TNBC patients, we used the UALCAN online database to analyze 1,097 primary breast cancer samples and 114 normal breast samples in TCGA according to molecular subtypes and histological classification." (PMID 33928086, 2021).
breast cancer (continued). "In addition, analysis using the HPA database showed that NSUN2 and NSUN6 were also abnormally expressed at the protein level in breast cancer tissues." (PMID 33928086, 2021). "NSUN2 (NOP2/Sun domain family, member 2), a major m5C-modifying methyltransferase (writer) of RNA, is highly expressed in various tumors such as the esophagus, liver, pancreas, cervix, prostate, kidney, bladder, thyroid, and breast cancers." (PMID 34926580, 2021). "Differential expression of NSUN2 was found in the matched breast cancer lesions and adjacent non-cancerous tissues, with a significant increase in NSUN2 levels in cancer cells." (PMID 27447970, 2017). "CCK-8 assay showed a significant increase in the number of NSUN2-overexpressing MCF-7 cells compared with the control after 72 h of culture (P<0.05), indicating that NSUN2 overexpression increases the proliferation of breast cancer cells." (PMID 27447970, 2017). "Similarly, 59 of 72 (81.9%) progesterone receptor (PR)-negative paraffin-embedded breast cancer tissues displayed moderate or strong nuclear NSUN2 staining, whereas 49 of 119 (41.2%) PR-positive tumor samples showed a decrease in NSUN2 staining (P=0.001)." (PMID 27447970, 2017). "Similarly, Western blot and IHC both showed that NSUN2 protein was upregulated in breast cancer tissues compared to their matched adjacent non-tumor tissues from the same patient." (PMID 27447970, 2017).
colorectal cancer (29 papers, 2016 to 2026). A primary or metastatic malignant neoplasm that affects the colon or rectum. "Among them, NSUN2 has been extensively reported to be significantly highly expressed in colorectal cancer (CRC) and is closely associated with glycolysis." (PMID 41406096, 2025). "Studies have shown that the copy number of the NSUN2 gene is significantly increased in colorectal cancer, and the RNA methyltransferase NSUN2 is associated with the oncogene MYC." (PMID 35614935, 2022). "Elevated NSUN2 levels in colorectal cancer are associated with poor patient survival." (PMID 40370440, 2025). "However, the roles and underlying molecular mechanisms of NSUN2‐mediated m5C modification in colorectal cancer (CRC) remain unclear." (PMID 38468490, 2024). "For instance, the accumulation of lactate in colorectal cancer cells not only activates the transcription of NSUN2, a 5-methylcytosine (m5C) methyltransferase, through H3K18la but also induces the lactylation of NSUN2 at the Lysine 356 residue." (PMID 40849487, 2025). "The high expression of NSUN2 in colorectal cancer inhibits miR-125b and thus promotes the expression of GRB2-associated binding protein, resulting in an enhanced migration rate of cancer cells." (PMID 40279954, 2025). "In gastric and colorectal cancers, NSUN2 inhibition effectively suppresses cancer cell proliferation and migration, while improving the response to chemotherapy." (PMID 40114967, 2025). "In colorectal cancer, NSUN2 suppresses miR-125b expression and enhances the expression of Grb-associated binding protein 2 (Gab2), thereby promoting cell migration." (PMID 40370440, 2025). "For example, NSUN2 is highly expressed in colorectal cancer (CRC), where it catalyzes m5C modification of ENO1 mRNA and enhances its stability via the reader protein YBX1, thereby promoting glycolysis and lactate production." (PMID 40859309, 2025). "Several studies have shown that NSUN2 is abnormally high in gastric and colorectal cancers, which is closely related to poor prognosis." (PMID 37168511, 2023). "For example, upregulated circNSUN2 (derived from NSUN2, another RNA methyltransferase with m6A sites) can be combined with multiple m6A readers in colorectal cancer cells." (PMID 36803376, 2023). "In accordance with our finding, copy number gain of NSUN2 has been reported in breast, oral, and colorectal cancers, which leads to the increased expression of it in cancers." (PMID 33365328, 2020). "Studies have reported that the protein level of NSun2 elevates in several kinds of cancers, such as colorectal cancers, glioblastoma, and so on." (PMID 33093178, 2020). "Clinicopathological features of NSUN2 expression in colorectal cancer (CRC) (Cohort 2)." (PMID 40156167, 2025). "In colorectal cancer, NSUN2 and YBX1 enhance ENO1 transcription via m5C RNA modification." (PMID 40843350, 2025). "This study identifies NSUN2 and YBX1 as the m5C “writer” and “reader” of ENO1 in colorectal cancer, culminating in a positive feedback loop involving the NSUN2/YBX1/m5C‐ENO1 signaling axis, thereby bridging the connection between metabolic reprogramming and epigenetic remodeling." (PMID 38769664, 2024). "In vitro and in vivo studies suggested that NSUN2 promoted colorectal cancer cell growth." (PMID 38468490, 2024). "In colorectal cancer (CRC), NSUN2 is also markedly upregulated in tumor tissues and is associated with poor patient prognosis." (PMID 41256859, 2025). "NSUN2 is the most studied NSUN family gene, which exhibits cancer promoting effects in various cancers such as lung cancer, liver cancer, and colorectal cancer." (PMID 41462962, 2025).
colorectal cancer (continued). "Overall, this positive feedback loop involving NSUN2, YBX1, and m5C-ENO1 further upregulated glycolysis and promoted the occurrence and development of colorectal cancer." (PMID 39925738, 2025). "Intriguingly a circRNA derived from the NSUN2 coding sequence called circNSUN2 (hsa_circ_0007380) has recently been identified as being frequently upregulated in patients with colorectal carcinoma (CRC) and predicts poorer patient survival." (PMID 32708015, 2020). "Similarly, in colorectal cancer (CRC), NSUN2, an m5C methyltransferase, is transcriptionally activated by H3K18la." (PMID 40859309, 2025). "In colorectal cancer (CRC) tissues and cells, NSUN2 and NSUN6 are significantly upregulated." (PMID 40114967, 2025).